VDR (vitamin D receptor)
Diseases named in the same sentence as VDR in open-access papers (continued):
Sharing a sentence is not in itself a finding about the gene and the disease.
kidney stone (19 papers, 2009 to 2025). "Studies reveal that multiple allelic variations in VDR, like ApaI, BsmI, TaqI, and Fok1, are associated with nephrolithiasis." (PMID 37007314, 2023). "The methylation of the VDR has also recently been investigated in the pathological state of recurrent kidney stone formation, given the significant association between the genetic variability of VDR and urinary stone formation risks." (PMID 38203278, 2023). "In the previous section, we reported how epigenetic changes in vitamin D receptor (VDR) were associated with an increased risk of nephrolithiasis." (PMID 36500991, 2022). "Pooled OR analysis between the urokinase (ApaLI) and VDR (ApaI, BsmI, FokI, and TaqI) gene polymorphisms and recurrent kidney stones." (PMID 33956883, 2021). "Pooled OR analysis between the urokinase (ApaLI) and VDR (ApaI, BsmI, FokI, and TaqI) gene polymorphisms and recurrent kidney stones among larger studies (N > 200 samples)." (PMID 33956883, 2021). "In comparison, the VDR-FokI (recessive model) gene polymorphism was associated with increased risk of recurrent kidney stones among the Asian population." (PMID 33956883, 2021). "Our study revealed the protective association of the VDR ApaI gene polymorphism against recurrent kidney stones in the dominant model (AA/Aa vs. aa)." (PMID 33956883, 2021). "Sub–analysis between the urokinase (ApaLI) and VDR (ApaI, BsmI, FokI, and TaqI) gene polymorphisms and recurrent kidney stones among Asian and Caucasian ethnicity." (PMID 33956883, 2021). "Our meta-analysis showed that urokinase-ApaLI (recessive model), VDR-ApaI (dominant model), and VDR-TaqI (heterozygous model) polymorphisms were significantly associated with decreased risk of recurrent kidney stones." (PMID 33956883, 2021). "It seems unlikely that the most frequent VDR polymorphisms play an important role in kidney stone formation." (PMID 29562593, 2018). "There are few studies that reported the association between VDR and kidney stone patients from India." (PMID 26107257, 2015). "In the present study, we investigated the association of VDR polymorphismsin kidney stone patients and controls in Indian population." (PMID 26107257, 2015). "We investigated polymorphisms in 200 kidney stone patients and 200 controls by direct sequencing of VDR, CaSR and CLDN14 genes." (PMID 26107257, 2015). "VDR gene polymorphisms may affect vitamin D signaling pathways, thus affecting kidney stone formation." (PMID 33956883, 2021). "In turn, VDR gene polymorphisms (ApaI, BsmI, TaqI, and FokI) may also influence VDR protein activity and expression, which play significant roles in kidney stone formation." (PMID 33956883, 2021). "The roles of VDR polymorphisms were also investigated in urolithiasis and nephrolithiasis." (PMID 27688524, 2016). "The role of these VDR polymorphisms in the etiology of IH nephrolithiasis remains to be explained." (PMID 18446382, 2009). "Additionally, research has also discovered a relationship between VDR polymorphisms and the occurrence of kidney stones, but the specific mechanism of this link remains unclear." (PMID 39329127, 2024). "Increased levels of VDR are found in circulating monocytes from patients with IH, and studies in a cohort of large French-Canadian families have revealed an association between IH nephrolithiasis and polymorphic loci from chromosome 12q12-q14, a region that contains the VDR gene." (PMID 18446382, 2009). "Until now, several SNPs in urokinase and vitamin D receptor (VDR) have been revealed to be related to recurrent kidney stones." (PMID 37332754, 2023). "It has been seen that genetic polymorphism of vitamin D receptor (VDR), Klotho, and chloride voltage-gated channels (CLCN) genes have a role in the formation of kidney stones." (PMID 37007314, 2023). "The pooled estimate of ORs for VDR was around 1.20 (95%CI:1.06–1.36), showing a significant difference between the two study groups (patients with nephrolithiasis and healthy controls)." (PMID 35846117, 2022).
kidney stone (continued). "Our findings suggested that protective effects against recurrent kidney stones were afforded by urokinase-ApaLI (recessive model), VDR-ApaI (dominant model), and VDR-TaqI (heterozygous model) gene polymorphisms." (PMID 33956883, 2021). "In this study, we investigated the pathogenetic role of CaSR, CLDN14 and VDR genes in kidney stone patients from the Indian population." (PMID 26107257, 2015). "In this meta-analysis, associations between the VDR BsmI gene polymorphism and recurrent kidney stones were not statistically significant in the allelic frequencies, homozygous, heterozygous, dominant, and recessive models." (PMID 33956883, 2021). "Associations between the VDR FokI polymorphism and recurrent kidney stone were not statistically significant in any models with healthy subject groups." (PMID 33956883, 2021). "Some groups identified VDR polymorphisms associated with kidney stone formation, but these results have not been confirmed in large populations." (PMID 29562593, 2018). "It has also been proposed that VDR could be more expressed in kidney stone formers’ tissues, and a high VDR expression has been shown in hypercalciuric patients’ leucocytes." (PMID 29562593, 2018). "For example, specific polymorphisms of the genes encoding vitamin D receptor (VDR), vascular endothelial growth factor (VEGF), androgen and estrogen receptors, calcium-sensing receptor (CASR), matrix Gla protein (MGP), and fibronectin (FN 1) were suggested to be a risk factor for nephrolithiasis." (PMID 24023817, 2013). "We aimed to check the association between promoter hypermethylation vitamin D receptor (VDR), calcium-sensing receptor (CaSR), and claudin 14 (CLDN14) genes in recurrent kidney stones." (PMID 35546405, 2022). "Nevertheless VDR does not seem to be a candidate gene of Kidney stone in our study population." (PMID 26107257, 2015).
osteoarthritis (19 papers, 2007 to 2026). A noninflammatory degenerative joint disease occurring chiefly in older persons, characterized by degeneration of the articular cartilage, hypertrophy of bone at the margins and changes in the synovial membrane. "On the other hand, several articles deny any statistically significant correlation between VDR genetic variants and the progression or onset of intervertebral disc degeneration or osteoarthritis." (PMID 37868452, 2023). "The function of VDR gene polymorphisms has been reported in many chronic pain studies, such as osteoarthritis, lumbar pain, and migraine." (PMID 36000140, 2022). "Several studies have investigated the links between the VDR polymorphism and cartilaginous tissue diseases (such as osteoarthritis of knee, hip, or inter-vertebral disks, lumbar disks, etc.), and a large majority of them revealed an association between them." (PMID 33919716, 2021). "Furthermore, polymorphisms in the vitamin D receptor have been linked to disc degeneration-related pathologies, such as osteoarthritis." (PMID 39275184, 2024). "Although the role of the VDR gene is implicated in chronic pain conditions such as migraine, osteoarthritis, and lower back pain, its significance in central hypersensitization-mediated pain pathways is unknown." (PMID 36000140, 2022). "The VDR gene is associated with osteoporosis, osteoarthritis, and prostate cancer." (PMID 17598904, 2007). "The VDR gene showed 6 haplotypes out of a possible 8 haplotypes, which captured 87–95% of the genetic variance for osteoarthritis patients and controls." (PMID 34073132, 2021). "Within tier 1, ten candidates have previously been studied in clinical trials of efficacy or in cohort studies of osteoarthritis (six arising from new signals: PPARD, NR3C1, VDR, MAPK14, IGF1R, and CHST3)." (PMID 34450027, 2021).
cervical carcinoma (18 papers, 2017 to 2025). A carcinoma arising from either the exocervical squamous epithelium or the endocervical glandular epithelium. "The impact of VDR gene polymorphisms on treatment efficacy also warrants further investigation, as certain VDR genotypes have been associated with increased susceptibility to cervical cancer." (PMID 41245397, 2025). "At the tissue level, downregulation of VDR expression in cervical cancer specimens is closely associated with elevated expression of immune exhaustion markers, implicating the VD–VDR signaling axis as a potential regulator of TIME remodeling." (PMID 41245397, 2025). "In summary, VD and VDR emerge as potential pivotal factors in the occurrence and progression of cervical cancer, potentially reducing disease risk." (PMID 38230221, 2024). "Several studies have investigated the relationship between vitamin D (VD) and its receptors (VDR) and the risk of cervical cancer." (PMID 38230221, 2024). "This study was proposed to elaborate on previous research regarding VD and VDR and cervical cancer, and to discuss the function and the underlying mechanisms of VD and VDR in cervical cancer." (PMID 38230221, 2024). "This review also briefly discussed the association between VDR gene polymorphisms and cervical cancer, albeit a comprehensive elucidation of this relationship remains an ongoing research endeavor." (PMID 38230221, 2024). "Although epidemiological studies have established associations between VD, VDR and cervical cancer susceptibility, the empirical support for their preventive efficacy remains notably reliant on a paucity of clinical trial studies." (PMID 38230221, 2024). "Epidemiological studies have established associations between VD, VDR, and cervical cancer susceptibility." (PMID 38230221, 2024). "Several studies have investigated associations between VD, VDR and cervical cancer in vitro studies 47, 54-58." (PMID 38230221, 2024). "Such endeavors will undoubtedly advance our understanding of the association between VDR gene polymorphism and cervical cancer." (PMID 38230221, 2024). "The FOKI f allele is associated with an increased risk of cervical cancer and most other cancers, possibly due to its reduced VDR activity." (PMID 36440356, 2022). "In conclusion, this study is the first to demonstrate the role of VDR polymorphisms, especially Taq1 polymorphism in cervical cancer risk among Northeastern Thai women." (PMID 33112551, 2020). "Certain gene polymorphisms may reduce VDR activity and responsiveness to calcitriol, thereby leading to the progression of cervical cancer." (PMID 38230221, 2024). "While epidemiological studies have demonstrated associations between VD, VDR and a reduced risk of cervical cancer, and certain mechanisms have been investigated, the precise mechanisms by which VD and VDR influencing cervical cancer remain incompletely understood and warrant further exploration." (PMID 38230221, 2024). "Therefore, the underlying mechanisms of different VDR gene polymorphisms in cervical cancer remain to be further investigated." (PMID 36440356, 2022). "Hence, this study provides the first report regarding the analysis of VDR polymorphisms (Fok1, Apa1 and Taq1) individually and VDR haplotype on cervical cancer risk among Thai population." (PMID 33112551, 2020). "Thus, the role of VDR genetic variation on cervical cancer susceptibility is most likely influenced by the presence of the C allele of Taq1 which produced less VDR activity and less responsive to calcitriol." (PMID 33112551, 2020). "Our finding revealed an association between VDR polymorphisms and cervical cancer risk." (PMID 33112551, 2020). "This study aimed to explore whether VDR polymorphisms (Fok1, Apa1 and Taq1) are associated to the cervical cancer in Thai population." (PMID 33112551, 2020). "Hence, further studies should consider gene-environment interaction to clarify the role of calcitriol and VDR on cervical cancer susceptibility." (PMID 33112551, 2020).
cervical carcinoma (continued). "In addition, while the association between VDR gene polymorphisms and cervical cancer has been elucidated to some extent, there remains an empirical void concerning the mechanistic underpinnings of these polymorphic loci changes in the context of HPV infection and VD." (PMID 38230221, 2024). "This is also in agreement with the effect on cervical cancer cells SiHa and HeLa wherein enhanced VDR expression and activity were observed along with the CYP27A1 and CYP27B1 gene upregulation up on treatment with calcitriol." (PMID 40920750, 2025). "VD/VDR signaling suppresses cervical-cancer cell growth through coordinated inhibition of the cell cycle and down-regulation of HPV oncogenes." (PMID 41245397, 2025). "Studies have shown that promoter hypermethylation of the VDR gene can lead to reduced VDR expression in cervical cancer cells." (PMID 38230221, 2024). "Our literature research found that VD, VDR and their related signaling pathways played indispensable roles in the occurrence and progression of cervical cancer." (PMID 38230221, 2024). "Nevertheless, the exact mechanisms by which histone modifications interact with VDR signaling in cervical cancer cells remain an active area of research." (PMID 38230221, 2024). "Recent studies have shown that certain VDR polymorphisms are associated with a high risk of HPV16-associated CIN2 (cervical intraepithelial neoplasia grade 2) and cervical cancer." (PMID 38732639, 2024). "Notably, these studies did not consider gene-environment interactions, for example, skin color may affect the process of skin synthesis of VD under light, and circulating VD levels may interact with the VDR gene variants to have an impact on cervical cancer risk." (PMID 38230221, 2024). "Compared to healthy cervical tissue, cervical carcinomas have a greater fraction of the vitamin D receptor (VDR) and the anabolic and catabolic vitamin D hydroxylases." (PMID 39337406, 2024). "In this review, we analyzed the impacts of VD and VDR on cervical cancer and related mechanisms, and discussed the effects of VD, calcium, and other vitamins on cervical cancer." (PMID 38230221, 2024). "We carried out similar experiments on our NRs in other cell lines: on RAR in HeLa cervical carcinoma and on VDR in Caco-2 colorectal adenocarcinoma cells." (PMID 36639026, 2023). "Cervical cancer cells express an autocrine vitamin D metabolising system (VDMS) comprised of a vitamin D receptor, vitamin D catabolic enzyme (CYP24A1), and the activating enzyme of 25-hydroxycholecalciferol (25(OH)D3), CYP27B1." (PMID 36979850, 2023). "This study analyzed the relationship between VDR polymorphism and HPV16-positive CIN2+ patients in Shanxi women, aiming to provide a theoretical basis for reducing the occurrence of cervical cancer." (PMID 36440356, 2022). "This project aimed to investigate the relationship between VDR SNPs (FOKI, BsmI, ApaI, and TaqI) and the risk of CIN2/3 and cervical cancer in Shanxi women." (PMID 36440356, 2022). "Depending on the cell line derived from cervical cancer, differences in VDR activity are observed." (PMID 38732639, 2024). "The literature on the relationship between cervical cancer and the VDR is limited." (PMID 38230221, 2024). "Therefore, further in-depth investigation is required to elucidate the role of VDR upregulation in cervical cancer progression, prognosis and response to treatment." (PMID 38230221, 2024). "Interestingly, recent studies found that Fok1 and TaqI VDR polymorphisms are associated with a high risk of HPV16-dependent CIN2 and cervical cancer." (PMID 37240017, 2023). "The study of VDR genetic polymorphisms is one approach to understand interindividual susceptibility to cervical cancer which have not been evaluated previously." (PMID 33112551, 2020). "Moreover, while altered VDR expression due to methylation changes is observed, the downstream effects on gene expression and apoptosis may differ among cervical cancer subtypes." (PMID 38230221, 2024).
cervical carcinoma (continued). "Therefore, it is reasonable to speculate that VD may inhibit the progression of cervical cancer by binding with VDR, potentially implicating the Wnt/β-catenin signaling pathway as a target for intervention." (PMID 38230221, 2024). "From previous studies, we suspected that cervical cancer apoptosis and autophagy were closely related to HPV18E6/7, PD-L1 and VDR expression." (PMID 34974811, 2022). "Cervical cancer cells show a higher expression of VDR than cells of healthy tissue, but it is not recommended as a prognostic factor for cervical cancer." (PMID 38732639, 2024). "It has been reported that calcitriol has regulatory actions on both the expression of some components of the microRNA biogenesis machinery and the microRNA expression in VDR-positive SiHa and HeLa cells but not in C33A VDR-negative cervical cancer cells." (PMID 37240017, 2023). "The vitamin D endocrine system, primarily mediated by its main metabolite calcitriol and the vitamin D receptor (VDR), plays a critical role in numerous human physiological processes, ranging from calcium metabolism to the prevention of various tumors, including cervical cancer." (PMID 40168262, 2025). "It is not known why C33A lacks VDR; however, these cells might be used as negative controls to validate calcitriol-mediated effects in cervical cancer." (PMID 37240017, 2023). "However, VDR protein expression may not be a prognostic factor in cervical cancer." (PMID 38698459, 2024).
coronary artery disease (18 papers, 2013 to 2023). "The association of vitamin D level and vitamin D receptor (VDR) gene polymorphisms with the prevalence of coronary artery disease (CAD) has been evaluated in various studies; however, the reported results were inconsistent." (PMID 36882686, 2023). "A significant correlation between the Bsm I (rs1544410) VDR polymorphism and vitamin D activity in coronary artery disease (CAD) patients following myocardial infarction was also found in a study by Raljevi and colleagues in 2021." (PMID 37259407, 2023). "Patients with coronary heart disease who experienced a cardiac event were genotyped for the VDR polymorphism rs1544410." (PMID 37259407, 2023). "Overall and subgroup analysis of the associations of the four VDR polymorphisms with coronary artery disease susceptibility." (PMID 36190985, 2022). "The gene encoding the vitamin D receptor (VDR) is considered in many studies to be a good candidate responsible for susceptibility to several diseases such as coronary artery disease (CAD)." (PMID 33564343, 2021). "Characteristics of included studies about the four VDR polymorphisms and coronary artery disease." (PMID 36190985, 2022). "In addition to deficiency, reduced ECFC expression of the vitamin D receptor has been linked to coronary artery disease; high glucose conditions also reduced vitamin D receptor expression in an in vitro diabetic cellular model." (PMID 30042945, 2018). "Δ phosphate, Δ calcium and Δ albumin were calculated as valueFollow up−valueBaseline Abbreviations: Body mass index (BMI); Vitamin D receptor activators (VDRA); coronary heart disease (CHD); peripheral arterial occlusive disease (PAOD); Interleukin-6 (IL-6)." (PMID 29042624, 2017). "The presence of VDR in vascular smooth muscle cells and endothelial cells coupled with the ability of vascular tissues to activate vitamin D locally suggests a role vitamin D may play in normal vascular physiology and its role in the prevention of ischemic heart disease." (PMID 24729966, 2014).